RN7SL559P (RNA, 7SL, cytoplasmic 559, pseudogene)
Gene: Miscellaneous RNA gene on chromosome 1 (28,031,884 to 28,032,180, reverse strand). Ensembl gene ENSG00000240750.
Homologues: Orthologues: chimpanzee Metazoa_SRP (99% identical), macaque Metazoa_SRP (92% identical). Paralogues in human: RN7SL2 (86% identical), RN7SL1 (86% identical), RN7SL3 (86% identical), RN7SL220P (84% identical), RN7SL679P (83% identical), RN7SL113P (83% identical), RN7SL126P (83% identical), RN7SL397P (83% identical), RN7SL218P (82% identical), RN7SL712P (82% identical), RN7SL732P (82% identical), RN7SL769P (82% identical), and 700 more.